S100A8 (S100 calcium binding protein A8)
Diseases named in the same sentence as S100A8 in open-access papers (continued):
Sharing a sentence is not in itself a finding about the gene and the disease.
vulvovaginal candidiasis (3 papers, 2020 to 2025). Infection of the vulva and vagina with a fungus of the genus CANDIDA. "During vulvovaginal candidiasis, IL-22-deficient mice also showed pronounced neutrophil recruitment to the vaginal epithelium, followed by increased production of AMPs, such as S100A8 and S100A9, as well as elevated tissue damage." (PMID 32517114, 2020). "It was presumed that cytokine secretion by α-GalCer-stimulated iNKT cells increased the number of vaginal NK cells and CD8+ T cells, accumulating leukocyte infiltrations and increased S100A8, which resulted in improvement of vulvovaginal candidiasis." (PMID 34784362, 2021). "Additionally, our earlier research on C. albicans vulvovaginal candidiasis demonstrated that S100A8 concentration was positively correlated with vaginal inflammatory cell infiltration." (PMID 41060043, 2025). "Our results implicated that leukocyte infiltrations and S100A8 expression accordant with iNKT cells, NK cells, and CD8+ T-cells played coordinately protective roles against vulvovaginal candidiasis, although further investigation is necessary to elucidate these points." (PMID 34784362, 2021). "In vulvovaginal candidiasis, it was reported that infiltrating cells into vaginal lumen after C. albicans inoculation were predominantly neutrophils, and these cells were main sources of S100A8; however, these factors had no apparent effect on vaginal fungal burden." (PMID 34784362, 2021).
Acute hepatitis (2 papers, 2018 to 2020). Acute hepatic injury resulting from inflammation typically accompanied by increased serum alanine transaminase activity. "Higher expression of S100A8 during acute hepatitis in both trimesters and additionally S100A12 in the third trimester, with normal expression of S100A9 suggests similar role in the PR patients as well." (PMID 32012176, 2020).
acute lung injury (2 papers, 2017 to 2021). A condition of lung damage that is characterized by bilateral pulmonary infiltrates (pulmonary edema) rich in neutrophils, and in the absence of clinical heart failure. "Similar to COPD, it appears that S100A8, S100A9, and the S100A8/A9 heterodimer have opposite effects in acute lung injury (ALI)." (PMID 34239729, 2021).
acute tonsillitis (2 papers, 2017 to 2021). An acute inflammation of the tonsils caused by viruses or bacteria. "In this prospective study, we examined S100A8/A9 levels in the serum and saliva and its potential role as a promising and helpful biomarker to differentiate between acute tonsillitis (AT), PC, and PTA." (PMID 29180834, 2017). "Systemic S100A8/A9 levels were increased in the serum of patients with acute tonsillitis compared to healthy controls (3450 ± 650 ng/ml versus 550 ± 90 ng/ml, p < 0.001)." (PMID 29180834, 2017). "We proposed an influence of this S100A8/A9 complex on the pathomechanism of recurrent tonsillitis and could also observe elevated levels of this complex in serum of patients with recurrent episodes of acute tonsillitis." (PMID 34187480, 2021).
AIDS (2 papers, 2020 to 2022). A syndrome resulting from the acquired deficiency of cellular immunity caused by the human immunodeficiency virus (HIV). "We assessed the distribution of S100A8/9 and S100A12 with regard to disease activity in the AIDS+SURFS group." (PMID 31948488, 2020).
allergic contact dermatitis (2 papers, 2014 to 2023). An inflammatory skin condition caused by an immune response to direct contact between the skin and an allergen. "It showed that sustained exposure of S100A8/S100A9 hindered the differentiation and antigen presentation capacity of DCs, thereby leading to attenuated T cell response in allergic contact dermatitis." (PMID 37337301, 2023). "Here, using optical molecular imaging, we demonstrate that the alarmin S100A8/S100A9 serves as a sensitive local and systemic marker for the detection of even sub-clinical disease activity in inflammatory and immunological processes like irritative and allergic contact dermatitis." (PMID 25098555, 2014).
and mouth disease (2 papers, 2018 to 2024). "For example, increases in plasma MPO and S100A8/A9 levels have been reported in hand, foot, and mouth disease (HFMD) patients, and Andro-S was demonstrated to be clinically effective against HFMD by reducing fever and inflammation." (PMID 30174607, 2018).
androgen alopecia (2 papers, 2025). "S100A8 plays a role in promoting hair follicle stem cell proliferation by mediating the Wnt–β-catenin signaling pathway against androgenic alopecia." (PMID 41380997, 2025). "The continuous expression of S100A8 from D75 to D170 in human hair follicle development models suggests that S100A8 may serve as a potential target protein for the treatment of androgenic alopecia." (PMID 41380997, 2025).
aphthous ulcers (2 papers, 2016 to 2025). "Increased levels of transcripts for monocyte‐specific genes (e.g. CD14, NOD2, S100A8/A9; Clusters 8 and 14) indicate specific infiltration of these cells into the aphthous ulcers." (PMID 40386941, 2025).
autoinflammatory syndrome (2 papers, 2020 to 2021). A group of disorders of the innate immune system characterized by attacks of seemingly unprovoked inflammation without significant levels of either autoantibodies or autoreactive T cells more characteristic of autoimmune disease. "Levels of S100A8/9 and S100A12 are an indicators of disease activity in sJIA but not in other autoinflammatory syndromes or nsJIA." (PMID 31948488, 2020).
B-cell chronic lymphocytic leukemia (2 papers, 2016 to 2022). "The calcium-binding proteins S100A4, S100A8, and S100A9 are upregulated in chronic lymphocytic leukemia (CLL), while the S100A9 promotes NF-κB activity during disease progression." (PMID 35805957, 2022).
calculus (2 papers, 2021 to 2024). "Among the 20 common stone matrix proteins, S100A8 and S100A9 were the most frequently detected and they appeared in all kinds of urinary stones." (PMID 34395096, 2021).
chronic eosinophilic leukemia (2 papers, 2020 to 2023). "S100A8 has been demonstrated inducing apoptosis of imatinib-resistant human eosinophilic leukemia cell lines." (PMID 37065476, 2023). "In conclusion, this study demonstrates that S100A8 and S100A9 trigger apoptosis of chronic eosinophilic leukemia by induction of intrinsic apoptosis and suppression of FIP1L1-PDGFRα+-mediated proliferation." (PMID 32903598, 2020). "This study was, therefore, undertaken to determine the antitumor effects of S100A8 and S100A9 on eosinophils of chronic eosinophilic leukemia." (PMID 32903598, 2020). "S100A8 and S100A9 blocked tumor progression of xenografted EoL-1 and EoL-1-IR cells in NOD-SCID mice and evoked apoptosis of eosinophils derived from hypereosinophilic syndrome as well as chronic eosinophilic leukemia." (PMID 32903598, 2020).
chronic heart failure (2 papers, 2017 to 2024). "Recently increased levels of IL-8 in the tissue of tonsils with PTA compared to tonsils derived from patients with recurrent tonsillitis were observed, and strong positive correlations of S100A8/A9 and IL-8 have been described in association with congestive heart failure." (PMID 29180834, 2017).
cognitive decline (2 papers, 2020 to 2023). "Similarly, disease associated microglia (DAM) cells, assumed to have a protective function, have low S100a8 and S100a9 levels; while granulocytes/neutrophils have high S100a8 and S100a9 expression and may promote AD-like pathology and cognitive decline." (PMID 32469975, 2020).
colorectal adenoma (2 papers, 2012 to 2016). An adenoma that arises from the colon or rectum. "Plasma levels of S100A8 and S100A9 increase appreciably in patients with colorectal adenomas and established CRCs." (PMID 23166536, 2012).
corneal infection (2 papers, 2019 to 2024). A viral or bacterial infectious process affecting the cornea. "We determined the expression pattern of AMPs elicited in corneal infections caused by S. pneumoniae in patients for the first time, and we found significantly increased expressions of hBD2 and 3, S100A8, S100A9, S100A12, LL-37, lipocalin, Rnase7, and hepcidin." (PMID 30845777, 2019).
coronary aneurysm (2 papers, 2024). Abnormal balloon- or sac-like dilatation in the wall of coronary vessels. "On the other hand, persistent elevation of the plasma levels of S100A8 after IVIG therapy was reported to be associated with increased risk of coronary aneurysms in KD patients." (PMID 38798352, 2024). "Notably, research into IVIG treatment for KD has revealed elevated levels of S100A8 and S100A9 in the serum of KD patients during the acute phase, with a subsequent decline in levels post-treatment, except in cases where patients developed coronary aneurysms." (PMID 39350793, 2024).
cyst (2 papers, 2013 to 2020). A sac-like closed membranous structure that may be empty or contain fluid or amorphous material. "S100A8 with S100A9 complex is believed to facilitate the cyst migration in PCOS condition." (PMID 32478041, 2020). "The high evident protein interaction network studies between PCOS biomarkers, cancer invasion markers, and the interactors of S100A8 confirm that this protein has strong interaction with other selective PCOS biomarkers, which may be associative in the immature cyst invasion process." (PMID 32478041, 2020). "S100A8 and S100A9, also known as Calgranulins A and B, were first identified in cyst fluid and serum as up regulated in ovarian cancer, but absent or negative in benign cysts." (PMID 23557354, 2013).
diabetic retinopathy (2 papers, 2023 to 2024). "This indicates a role of S100A8 in the pathogenesis of diabetic retinopathy and its possible usefulness as a prognostic biomarker." (PMID 38153746, 2023).
endometrial tumor (2 papers, 2023 to 2025). "Regarding regional draining nodes in low- and high-grade endometrial tumors, the former showed lower S100A8/A9 and CD163 values." (PMID 36835583, 2023). "Regarding low- and high-grade endometrial tumors’ regional draining nodes, the former showed lower S100A8/A9 (2.273 ± 2.947 vs. 10.154 ± 6.543, p = 0.0001) and CD163 (5.136 ± 6.198 vs. 9.077 ± 8.46, p = 0.0505) values." (PMID 36835583, 2023). "Collectively, these findings suggest that in EC, S100A8 serves as a biomarker of immune context rather than a direct driver of tumor progression, highlighting the importance of immune–epithelial interactions in endometrial tumor biology." (PMID 41303754, 2025).
familial Mediterranean fever (2 papers, 2015 to 2018). Familial Mediterranean fever (FMF) is an autoinflammatory disorder characterized by recurrent short episodes of fever and serositis resulting in pain in the abdomen, chest, joints and muscles. "The very high levels of S100A8/A9 of >200 μg/ml and higher observed in some of our patients are usually only seen in patients suffering from rare syndromes such as Familial Mediterranean Fever." (PMID 25860480, 2015).
giant cell arteritis (2 papers, 2018 to 2019). "Additionally, higher concentrations of S100A8/A9 bound to endothelial cells was indicative of active disease, which has been similarly observed with S100A12 in giant cell arteritis." (PMID 30533405, 2018).
Hepatic steatosis (2 papers, 2023 to 2025). Steatosis is a term used to denote lipid accumulation within hepatocytes. "To address this, we generated macrophage-specific S100a8-KO mice and observed a significant reduction in hepatic steatosis, accompanied by decreased expression of the fatty acid transporter CD36." (PMID 41178716, 2025). "Detailed investigations incorporating markers that distinguish monocyte-derived macrophages, resident macrophages, and other macrophage subsets will be essential to accurately identify the specific origins of S100A8+ macrophages in the liver and their role in the pathogenesis of hepatic steatosis." (PMID 41178716, 2025). "The current study provides evidence that elevated expression of CCN3 in the liver of macrophage-specific S100a8-KO mice inhibits CD36 expression and suppresses hepatic steatosis." (PMID 41178716, 2025).
hidradenitis suppurativa (2 papers, 2022 to 2023). A chronic suppurative and cicatricial disease of the apocrine glands occurring chiefly in the axillae in women and in the groin and anal regions in men. "Nevertheless, S100A8 may enhance inflammation in patients with hidradenitis suppurativa by stimulating keratinocytes to increase the production of proinflammatory mediators and attracting other immune cells." (PMID 36235175, 2022).
intracranial aneurysms (2 papers, 2022 to 2023). "S100A8/A9 is present in the wall and thrombus lumen of enlarged intracranial aneurysms." (PMID 37217870, 2023). "Venous S100A8/A9 level is elevated in both ruptured intracranial aneurysms (rIAs) and unruptured intracranial aneurysms (uIAs), and may be a sign of aneurysm wall inflammation." (PMID 37217870, 2023). "Given its critical role in vascular inflammation, S100A8/A9 may be used as a biomarker and potential therapeutic target for intracranial aneurysms." (PMID 37217870, 2023).
intrauterine growth restriction (2 papers, 2014 to 2025). "We took into consideration the last 15 years, using specific keywords such as pre-eclampsia, intrauterine growth restriction, inflammation, S100A8, S100A9, and calprotectin." (PMID 41155408, 2025).
invasive breast carcinoma (2 papers, 2014 to 2021). A carcinoma that infiltrates the breast parenchyma. "Thus, in this study, we aimed to evaluate the difference in expression of S100A8 in TCs and ICs between pre-invasive carcinoma and invasive carcinoma of the breast, and we investigated the clinicopathologic significance of its expression." (PMID 33146829, 2021). "Expression of S100A8 in invasive breast carcinoma has been studied using immunohistochemistry." (PMID 33146829, 2021). "Thus, pre-invasive and invasive breast carcinomas with high S100A8+ IC infiltration could be a target for close observation and aggressive additional treatment." (PMID 33146829, 2021). "This study was conducted to evaluate the expression of S100A8, a well-known MDSC marker, and the significance of its expression in pre-invasive and invasive breast cancers." (PMID 33146829, 2021). "Expression of S100A8 in pre-invasive breast carcinoma, however, has not been studied widely although it is hypothesized that S100A8 exerts its pro-tumorigenic role in pre-invasive cancer as a MDSC-associated molecule." (PMID 33146829, 2021).
invasive carcinoma (2 papers, 2021). A carcinoma that is not confined to the epithelium, and has spread to the surrounding stroma. "In survival analyses, infiltration of S100A8+ ICs was associated with ipsilateral breast recurrence in pre-invasive carcinoma, and it was found to be an independent poor prognostic factor in invasive carcinoma." (PMID 33146829, 2021). "Thus, it seems that S100A8 is expressed in TCs of pre-invasive carcinoma just as much as invasive carcinoma in association with aggressive clinicopathologic features of tumor." (PMID 33146829, 2021). "Besides S100A8+ IC, the presence of PD-L1+ IC was associated with ipsilateral breast recurrence in pre-invasive carcinoma (p = 0.001)." (PMID 33146829, 2021). "In addition, we have shown that S100A8 expression in TCs was associated with poor clinicopathologic features in both pre-invasive and invasive carcinomas as reported in previous studies." (PMID 33146829, 2021). "Similarly, infiltration of S100A8+ IC was associated with decreased ipsilateral breast recurrence-free survival in the same subgroups in pre-invasive carcinomas." (PMID 33146829, 2021). "In invasive carcinoma, S100A8+ TCs comprised up to 100% of TCs, and S100A8+ ICs were also found in up to 50% of a tumor area." (PMID 33146829, 2021). "Next, we evaluated the patients’ clinical outcome in relation to the presence of S100A8+ TCs or infiltration of S100A8+ ICs in pre-invasive and invasive carcinomas." (PMID 33146829, 2021). "In pre-invasive carcinoma, S100A8 expression was detected in up to 90% of TCs, and S100A8+ ICs were found in up to 50% of a tumor area." (PMID 33146829, 2021). "S100A8 expression in TCs and ICs showed a weak positive correlation in pre-invasive carcinoma (rho = 0.260) and a moderate positive correlation in invasive carcinoma (rho = 0.452) as shown in the scatter plots." (PMID 33146829, 2021). "In this study, CD8+ TIL infiltration also showed a positive correlation with S100A8+ IC infiltration in pre-invasive and invasive carcinomas." (PMID 33146829, 2021). "It seems that the amount and composition of TIL subsets go through a dynamic change from pre-invasive carcinoma to invasive carcinoma, and this change is likely to be related to the early-existing S100A8+ ICs." (PMID 33146829, 2021). "Infiltration of S100A8+ ICs was revealed as a poor prognostic indicator in pre-invasive and invasive carcinomas, especially in hormone receptor-positive subgroup." (PMID 33146829, 2021). "S100A8 expression in TCs and ICs showed a positive correlation in pre-invasive carcinoma and invasive carcinoma." (PMID 33146829, 2021). "In this study, we compared S100A8 expression in pre-invasive and invasive carcinoma of the breast and observed significantly higher infiltration of S100A8+ ICs in invasive carcinoma than pre-invasive carcinoma." (PMID 33146829, 2021). "When comparing the infiltration of S100A8+ ICs between pre-invasive carcinoma and invasive carcinoma as a continuous variable, S100A8+ ICs were significantly higher in invasive carcinomas than in pre-invasive carcinomas (p = 0.010)." (PMID 33146829, 2021). "The positive correlation between S100A8+ ICs and other IC subset was more prominent in invasive carcinoma than in pre-invasive carcinoma." (PMID 33146829, 2021). "In pre-invasive carcinoma, infiltration of S100A8+ IC revealed weak positive correlations with infiltration of CD4+, CD8+, and FOXP3+ TIL and PD-L1+ IC (rho 0.209–0.281)." (PMID 33146829, 2021). "Generally, TIL subset infiltration was significantly higher in S100A8+ IC (+) group than in S100A8+ IC (−) group in both pre-invasive and invasive carcinoma as a whole (all p < 0.01)." (PMID 33146829, 2021).